CDH23 (cadherin related 23)
Diseases named in the same sentence as CDH23 in open-access papers (continued):
Sharing a sentence is not in itself a finding about the gene and the disease.
hearing loss (continued). "This study revealed that there are several common variants in the Japanese hearing loss population, with p.P240L accounting for 32.9% of all CDH23 variants in the Japanese population, followed by p.R1588W (14.5%), p.R2029W (10.3%) and p.E956K (4.7%)." (PMID 35020051, 2022). "We have previously reported the clinical characteristics of CDH23-related hearing loss to be high-frequency-involved progressive hearing loss." (PMID 35020051, 2022). "We have previously reported the mutational spectrum and clinical features of CDH23-associated hearing loss, as well as certain genotype/phenotype correlations." (PMID 35020051, 2022). "Taken together, it has become clear that CDH23 variants are likely to cause a broad range of hearing loss phenotypes." (PMID 35020051, 2022). "After conditioning on independent common variants at each locus, the rare variant and gene burdens remained associated with hearing loss (maximum conditional P ≤ 3 × 10−5) except for the CDH23 Asn1103Ser association (conditional P = 0.79)." (PMID 35661827, 2022). "The two sisters of Case #11 with nonsyndromic hearing loss exhibited two variants in CDH23, a gene that encodes a putative cell adhesion protein with multiple cadherin-like domains." (PMID 34997062, 2022). "It should be noted that variants of CDH23 are reported to be associated with noise-induced hearing loss." (PMID 35020051, 2022). "In all detected CDH23 variants, p.Pro240Leu and p.Arg1588Trp are the most common variants in the Japanese hearing loss population." (PMID 36468022, 2022). "As a result of the large-cohort MPS analysis, we identified 307 probands with CDH23-associated hearing loss." (PMID 35020051, 2022). "Various combinations of biallelic variants were detected and a total of 307 subjects were diagnosed as suffering hearing loss caused by CDH23 variants." (PMID 35020051, 2022). "Mutations of the Cdh23 gene are involved in a spectrum of hearing impairments, including hearing loss with vision loss, Usher syndrome 1D, early-onset progressive hearing loss, and AHL in humans or mouse models." (PMID 32587610, 2020). "The impact of the defective CDH23 protein was observed in both syndromic and non-syndromic hearing loss forms." (PMID 32115674, 2020). "Although a digenic inheritance pattern of hearing impairment has been reported for heterozygous missense variants of ATP2B2 and CDH23, our findings indicate a monogenic cause of hearing impairment in cases with loss-of-function variants of ATP2B2." (PMID 30535804, 2019). "Case 135 was found to be compound heterozygote for variants in both EYS and CDH23; he was diagnosed clinically with RP and had a mild hearing impairment." (PMID 30718709, 2019). "Considering the relevance of CDH23 biomarker as a congenital hearing impairment gene and a good candidate gene for ARHI, risk associated studies for this particular biomarker should be replicated in large and different elderly populations." (PMID 30131691, 2018). "A statistical analysis was performed to compare the frequency of CDH23 mutation between the adult and pediatric hearing loss cohorts; a difference was shown with marginal significance (p = 0.051 by Fischer’s exact test)." (PMID 27792758, 2016). "SLC26A4 and CDH23 mutations were frequently identified in patients with severe to profound hearing loss, whereas KCNQ4 gene mutations and m.3243A>G mutations were frequently identified in patients with hearing loss ranging from mild to moderate." (PMID 27627659, 2016). "CDH23 related hearing loss is known to be associated with its role in the tip links of the inner ear hair cells." (PMID 27792758, 2016). "The clinical characteristics (onset of hearing loss, progression, audiologic evaluation) of the hearing-impaired subjects carrying CDH23 mutations were also documented." (PMID 26264712, 2015).
hearing loss (continued). "In this study, the relative genetic contribution of the CDH23 mutation to nonsyndromic arSNHL was estimated in a Korean pediatric hearing loss cohort, and the genetic load of GJB2 and SLC26A4 was documented." (PMID 26264712, 2015). "We also identified 26 non-synonymous variants in CDH23 coding exons from 16 hearing-loss patients and 30 Korean exomes." (PMID 24767429, 2014). "Although the precise contribution made by such mutations needs to be determined using a larger patient cohort, our data indicate that mutations in the CDH23 gene are one of the most important causes of non-syndromic hearing loss in East Asians." (PMID 24767429, 2014). "In this study, both families with ARNSHL caused by CDH23 mutations carried the p.Pro240Leu mutation and, additionally, two of 93 hearing-loss patients were heterozygous for the mutation." (PMID 24767429, 2014). "Sanger sequencing revealed that the other subject with hearing loss (subject II:3) also had both heterozygous CDH23 and PCDH15 mutations." (PMID 24164807, 2013). "In Japanese, GJB2, SLC26A4, CDH23 and the 1555A>G mutation in the mitochondrial 12S rRNA are the major causes of hearing loss." (PMID 24053799, 2013). "In conclusion, a large cohort study using Taqman amplification-based mutation analysis indicated that mutations of the CDH23 gene are important causes of non-syndromic hearing loss." (PMID 22899989, 2012). "The present study is the first to demonstrate the prevalence of CDH23 mutations among non-syndromic hearing loss patients and indicated that mutations of the CDH23 gene are an important cause of non-syndromic hearing loss." (PMID 22899989, 2012). "Screening for gene mutations in CDH23, which has many exons, has lagged even though it is likely to be an important cause for hearing loss patients." (PMID 22899989, 2012). "In this study, we have applied two-step screening and identified a significant number of novel pathologic mutations of CDH23 responsible for non-syndromic hearing loss in a large cohort of patients." (PMID 22899989, 2012). "This variant corresponds to CDH23 c.7903G > T, p.V2635F and co-segregates perfectly with hearing loss in the extended kindred." (PMID 21917145, 2011). "The 2-LOD Snhl1 confidence interval contains 30 genes including Cdh23, which is involved in various forms of hearing loss in both mouse and human." (PMID 20628639, 2010). "Variants in the CDH23 gene may cause either syndromic hearing loss (Usher syndrome type ID) or non-syndromic hearing loss (DFNB12)." (PMID 40760574, 2025). "In humans, CDH23 is a well-established gene involved in congenital hearing loss." (PMID 41255877, 2025). "Human CDH23 is expressed in the sensory epithelium of the inner ear, where it is involved in maintaining the stereocilium organization of hair cells required for sound perception and equilibrioception, and CDH23 mutations are known to cause hereditary hearing loss." (PMID 40463242, 2025). "In conclusion, our study may shed light on deciphering the principal mechanism and provide a potential therapeutic method for congenital hearing loss under the condition of CDH23 mutation." (PMID 37575969, 2023). "Moreover, in a mouse model of hearing loss with a novel cadherin-23 (Cdh23) mutation erl mice treated with an intraperitoneal salubrinal injection exhibited a reduction in outer hair cell death and hearing loss." (PMID 37108509, 2023). "Also, the present results showed that most cases of CDH23-associated hearing loss are congenital/early onset." (PMID 35020051, 2022). "However, hearing loss due to CDH23 variants is a frequent cause of hearing loss, not only in the Japanese population, but also in many ethnicities, such as Netherlanders, Palestinians, Egyptians, and Jews (see Usami and Nishio 2021 for review)." (PMID 35020051, 2022).
hearing loss (continued). "Several mutations in CDH23 are associated with inherited hearing loss and blindness." (PMID 36359740, 2022). "Evaluation of seven different CDH23 mutations identified in five patients with hearing loss." (PMID 36468022, 2022). "Meanwhile, several recent studies have suggested that certain types of age-related hearing impairment (ARHI) and noise-induced hearing loss may also be associated with CDH23 variants." (PMID 35020051, 2022). "Collectively, these findings warrant further investigation to determine whether carriers of CDH23 mutations are at a high risk of developing CD and/or hearing loss." (PMID 36359740, 2022). "However, WES results identified a pathogenic variant CDH23:p.Arg1746Gln associated with hearing loss." (PMID 35186827, 2021). "As a result, Cdh23 is an important gene linked to hearing loss." (PMID 32587610, 2020). "CDH23 gene mutations may cause either Usher syndrome type 1D (USH1D) or non‐syndromic hearing loss (DFNB12)." (PMID 32027099, 2020). "Moreover, Cdh23 was also found to be susceptible to noise induced hearing loss, which is a different type of SNHL." (PMID 27792758, 2016). "We checked whether any variant from either ATP2B2 or PCDH15 can contribute to hearing loss in this family in trans with the p.P240L of CDH23 as a modifier or in a digenic fashion, as previously suggested." (PMID 27792758, 2016). "Most CDH23 missense mutations localized in the calcium-binding sequences were associated with nonsyndromic hearing loss, which was presumed to be attributable to the increased sensitivity of the cochlear function to calcium-dependent cell adhesion, compared to that of the retinal function." (PMID 26264712, 2015). "The higher prevalence of this DFNB12 allele of p.P240L compared to other CDH23 mutant alleles implies that in Koreans the nonsyndromic hearing loss (DFNB12) phenotype is more commonly associated with CDH23 mutations than is the syndromic hearing loss phenotype (USH1D)." (PMID 26264712, 2015). "Additionally, we identified 26 non-synonymous variants in the CDH23 coding exons from 16 hearing-loss patients and 30 Korean control exomes." (PMID 24767429, 2014). "In addition to these causative mutations, 26 non-synonymous variants were identified in the CDH23 coding exons from 16 hearing-loss patients and 30 Korean control exomes." (PMID 24767429, 2014). "The present study is the first to show that CDH23 mutations cause hearing loss in Koreans." (PMID 24767429, 2014). "Indeed, this was encountered in a hearing impairment subject whose causative mutation occurred within the CDH23 gene." (PMID 25047600, 2014). "Although we have not reached the final conclusion, it is most likely that these heterozygous cases are also related to CDH23 mutations because: 1) allele frequencies are found to be higher in the hearing loss group, and 2) the phenotype is similar to that of the patients with two mutations." (PMID 22899989, 2012). "We previously reported that four pathologic mutations were identified in 5 out of 64 Japanese families compatible with autosomal recessive inheritance, suggesting that CDH23-caused deafness may be commonly found among non-syndromic hearing loss patients." (PMID 22899989, 2012). "However, screening strategy of other hearing loss genes is difficult and Sanger sequencing of the candidate genes, such as CDH23, with many exons is time consuming." (PMID 22899989, 2012). "Furthermore, several mouse lines, which were deficient for antioxidant components, such as superoxide dismutase 1 (SOD1), glutathione peroxidase 1(GPX1), plasma membrane calcium ATPase 2(PMCA2) or Cadherin Related 23 (CDH23) showed also increased sensitivity to noise-induced hearing loss." (PMID 38397817, 2024). "However, CDH23:p.Arg1746Gln, a pathogenic variant, supports the underlying cause of hearing loss." (PMID 35186827, 2021).
hearing loss (continued). "This mutation might lead to a major disruption in CDH23 protein structure that may cause disturbance of stereocilia organization and hair bundle formation affecting the mechano-transduction process and, in turn, hearing loss." (PMID 32115674, 2020). "Furthermore, since it is possible to correct age-related hearing loss in mice by repairing a single mutation in the Cdh23 allele, it may be feasible to treat CDH23-related hearing loss in humans with gene therapy in the near future." (PMID 27792758, 2016). "Mutations in autosomal genes such as TMPRSS3, TMC1, USHIC, CDH23, and TMIE are recognized as causes of hereditary hearing loss." (PMID 39287240, 2024). "To investigate the association between hereditary hearing loss and vestibular function, we compared vestibular function and symptoms among patients with GJB2, SLC26A4, and CDH23 variants." (PMID 38720048, 2024). "Variants in MYO7A, USH1C, CDH23, PCDH15, and WHRN are also responsible for non-syndromic hearing loss associated with loci DFNB2 and DFNA11, DFNB18, DFNB12, DFNB23, and DFNB31, respectively." (PMID 38525684, 2024). "CDH23-associated hearing loss, along with SLC26A4, is the second or third most frequent type of hearing loss after GJB2-associated hearing loss." (PMID 35020051, 2022). "A series of studies indicated that CDH23 variants cause a broad range of phenotypes of non-syndromic hearing loss (DFNB12), from congenital profound hearing loss to high-frequency-involved progressive hearing loss." (PMID 35020051, 2022). "Variants in the CDH23 gene are known to be responsible for both syndromic hearing loss (Usher syndrome type ID: USH1D) and non-syndromic hearing loss (DFNB12)." (PMID 35020051, 2022). "Several variants of the USH1 genes, MYO7A, CDH23, and USH1G, sometimes with digenic inheritance, have been reported to be linked to atypical USH with variable age at onset and severity of the hearing loss and RP." (PMID 35353227, 2022). "Our series of studies demonstrated that CDH23 variants cause a broad range of phenotypes of non-syndromic hearing loss (DFNB12); from congenital profound hearing loss to late-onset high-frequency-involved progressive hearing loss." (PMID 35020051, 2022). "In humans, mutations in CDH23 (ENSG00000107736) are associated with early-onset hearing loss (USH1D and DFNB12), and have been implicated in cases of late-onset, progressive hearing loss." (PMID 35100259, 2022). "In this study, only three causative genes, MYO7A, CDH23 and USH2A with novel and known variants contributed to both RP and hearing loss." (PMID 31850270, 2019). "Up to now ATP2B2 has only been reported as a modifier, or in a digenic mechanism with CDH23 for hearing impairment in humans." (PMID 30535804, 2019). "In a Japanese study, CDH23 mutations were reported to be frequent after GJB2 and SLC26A4 in children and adults with hearing impairment." (PMID 27792758, 2016). "The most frequent causative genes for AR hearing loss, in order of frequency, are GJB2, SLC26A4, MYO15A, OTOF, CDH23, and TMC1, with at least 20 mutations of each reported." (PMID 26664958, 2015). "Mutations in the autosomal genes TMPRSS3, TMC1, USHIC, CDH23 and TMIE are known to cause hereditary hearing loss." (PMID 24416283, 2014). "Double heterozygous mutations of CDH23 and PCDH15 have been reported to be a digenic cause of hearing loss." (PMID 24164807, 2013). "Mutations in the CDH23 gene are known to be responsible for both Usher syndrome type ID (USH1D) as well as non-syndromic hearing loss (DFNB12), and molecular confirmation of CDH23 mutations is clinically important for diagnosis of these conditions." (PMID 22899989, 2012). "In conclusion, our analyses revealed novel compound heterozygous mutations in CDH23 associated with autosomal recessive NSHL, thereby expanding the mutational landscape of CDH23-related hearing loss and increasing knowledge about the CDH23 splice site variants." (PMID 39777619, 2025).
hearing loss (continued). "This was also supported by the fact that most of the patients had no delay in starting to walk; that is, there were not many cases of CDH23-related hearing loss with the Usher phenotype, as inferred from the clinical data." (PMID 35020051, 2022). "Second, our findings point to multiple genes that have been reported to cause Mendelian forms of hearing loss previously, including EYA4, CDH23, TRIOBP, and GJB2, the latter being the most commonly reported gene in autosomal-recessive non-syndromic hearing loss." (PMID 35580588, 2022). "The present study demonstrated CDH23 variants cause a broad range of phenotypes, from non-syndromic to syndromic hearing loss as well as from congenital to age-related hearing loss." (PMID 35020051, 2022). "CDH23 is a component of the tip-link that is directly connected to the stereocilia mechanotransduction channel complex, mutations of which causes nonsyndromic (DFNB12) and syndromic (USH1D) hearing loss in humans." (PMID 34568429, 2021). "It is also important to mention that CDH23, a disease-causing gene linked with hearing loss was not included in the design of gene panel." (PMID 35186827, 2021). "Four affected siblings with progressive hearing impairment in our study carried a known pathogenic missense CDH23 variant, previously known as the prelingual DFNB12 variant, in a trans configuration with another rare novel CDH23 missense variant." (PMID 33316915, 2020). "Similar to ARHGEF40 and BRD9, the function of CDH23 has not been established hitherto in spite of being implicated in Usher syndrome type ID and non-syndromic hearing loss." (PMID 32276436, 2020). "Mutant alleles of CDH23, a gene that encodes a putative calcium-dependent cell-adhesion glycoprotein with multiple cadherin-like domains, are responsible for both recessive DFNB12 nonsyndromic hearing loss (NSHL) and Usher syndrome 1D (USH1D)." (PMID 33316915, 2020). "Based on the data for more than 10,000 hearing loss patients, the present updated study clearly demonstrated that CDH23 variants cause a wide range of hearing loss from non-syndromic hearing loss (DFNB12) to syndromic hearing loss and Usher syndrome type ID (USH1D)." (PMID 35020051, 2022). "CDH23 variants cause a wide range of phenotypes, from non-syndromic hearing loss (DFNB12) to syndromic hearing loss and Usher syndrome type ID (USH1D)." (PMID 38790200, 2024). "Although GJB2 and SLC26A4 mutations were absent in our patients, our results show that CDH23 mutation caused ARNSHL in 2 of 13 (15%) affected Korean families and that 3 of 93 patients with hearing loss carried a heterozygous mutation." (PMID 24767429, 2014). "Novel mutations were identified in multiple other genes - CDH23, MYO15A, WFS1, and TECTA - that are known to be responsible for hearing loss but are not routinely evaluated, largely because of their size." (PMID 21917145, 2011). "Mutations of MYO7A, CDH23, USH1C, PCDH15, USH1G, and WHRN can cause non-syndromic recessive hearing impairment, and MYO7A variants are also associated with a non-syndromic dominant form of hearing impairment." (PMID 35353227, 2022).
Usher syndrome type 1D (32 papers, 2005 to 2025). "Biallelic variants disrupting CDH23 cause ARNSHL (DFNB12) and Usher syndrome type I (USH1D), characterized by congenital SNHL, vestibular dysfunction and early onset retinitis pigmentosa." (PMID 38534090, 2024). "Mutations in the CDH23 gene can cause Usher syndrome type 1D (USH1D) and non-syndromic deafness DFNB12." (PMID 41049429, 2025). "In addition to MYO7A (DFNA11, DFNB2, and Usher syndrome type I), OTOF (DFNB9), CDH23 (DFNB12 and Usher syndrome type I), and WHRN (DFNB31) are present within the hair cell or its stereocilia." (PMID 37289589, 2023).